TRPC6 (transient receptor potential cation channel subfamily C member 6)
Diseases named in the same sentence as TRPC6 in open-access papers (continued):
Sharing a sentence is not in itself a finding about the gene and the disease.
glioma (continued). "Consistent expression of TRPC1, TRPC3, TRPC5, and TRPC6 has been found in glioma cell lines and acute patient-derived tissues, which gives rise to small, nonvoltage-dependent cation currents and contributes to the resting conductance of glioma cells." (PMID 32963700, 2020). "Another study involving TRPC6 revealed that TRPC6 knockdown inhibited glioma cell invasion and angiogenesis, and they concluded that TRPC6 is required for development of the aggressive glioma phenotype." (PMID 25852478, 2015). "TRPC6 expression is elevated in breast, liver, and stomach cancers and in glioma." (PMID 25852478, 2015). "For instance, mRNA encoding TRPC1, TRPC6, TRPM7, TRPM8, TRPV4, and TRPML2 appeared up-regulated in GBM tumor specimens in comparison with normal tissues and their expression was found to increase with glioma tumor grade with the highest mRNA level found in GBM patient samples." (PMID 33928077, 2021). "Similarly to TRPC3, TRPC6 has been involved in different brain disorders such as neuronal damage in stroke, Aβ-production in Alzheimer’s disease and especially in the development and progression of glioma." (PMID 33240883, 2020). "Beside its role on cancer cell migration, inhibition of the hypoxia-induced TRPC6 expression has an effect in endothelial cell tube formation in vitro as it reduced the number of branch points, indicating that TRPC6 is essential for the angiogenic potential of glioma cells." (PMID 24204345, 2013). "Mechanistically, TRPC6 expression led to increased steady-state Ca2+, which led to increased NFAT expression in MG373 glioma cell lines." (PMID 36768856, 2023). "Several TRP channels have been studied as potential biological markers of glioma progression and prognosis, including TRPC1, TRPC6, TRPM2, TRPM3, TRPM7, TRPM8, TRPV1/2." (PMID 36768856, 2023). "There is a growing consensus that TRPV1, TRPV2, TRPM2, TRPM3, and TRML1 exert anti-tumorigenic properties in glioma, while TRPC1, TRPC6, TRPM7, TRPM8, and TRPML2 promote glioma growth and proliferation." (PMID 36768856, 2023). "In previous reports, TRPC1, TRPC3, TRPC6, TRPML1, and TRPML2 were proven to play crucial roles in glioma progression." (PMID 35625048, 2022). "The gene expression levels of TRPC1, TRPC3, and TRPC5 were significantly higher in low-grade glioma (LGG), while the levels of TRPC4, TRPC6, TRPM7, MCOLN1, MCOLN2, and MCOLN3 were significantly higher in high-grade glioma (HGG)." (PMID 35625048, 2022). "A previous study proved that the clinical value of TRPC1, TRPC6, TRPML1, and TRPML2 plays key roles in the diagnosis and prognosis of glioma patients." (PMID 35625048, 2022). "However, it remains unclear how TRPC6 regulates glioma development." (PMID 33508123, 2021). "TRPC6, another TRPC family member, regulates hypoxylation and stability of hypoxia-inducible factor-1 (HIF-1) in human glioma cells under hypoxic conditions." (PMID 34149360, 2021). "Glioma cell lines and surgical patient-derived tumors have revealed the expression of four TRP channels belonging to the TRP canonical subfamily that are TRPC1, TRPC3, TRPC5, and TRPC6." (PMID 33928077, 2021). "Thus, TRPC6 specifically regulates POX expression in human glioma cells, and their expression levels are inversely correlated in human glioma tissues." (PMID 33508123, 2021). "In human glioma, the expression of transient receptor potential canonical 6 (TRPC6), known as a channel protein, is upregulated and the inhibition of its expression or activities by RNAi or the dominant-negative form of TRPC6 (DNC6) suppresses glioma cell proliferation and glioma development." (PMID 33508123, 2021). "Interestingly, RhoA/ROCK pathway is activated by TRPC6 in other tissues such as the kidney, suggesting that this relation between TRPC6 and RhoA/ROCK might also play a role in glioma progression." (PMID 33240883, 2020). "We then asked how TRPC6 controls POX but not BAX, p21, or PTEN expression in human glioma cells." (PMID 33508123, 2021).
pulmonary hypertension (19 papers, 2012 to 2025). Increased pressure within the pulmonary circulation due to lung or heart disorder. "In humans, a single-nucleotide polymorphism (SNP) in the TRPC6 promoter region, which leads to elevated basal TRPC6 expression, is associated with an increased risk of idiopathic pulmonary hypertension." (PMID 41118703, 2025). "TRPC6 channels have been previously linked to CaSR-induced contraction, proliferation and migration of VSMCs in pulmonary arterial hypertension, and to CaSR-mediated rises in [Ca2 +]i in human aortic VSMCs." (PMID 28867591, 2017). "The relevance of TRPC6 channels for HPV is further supported by the fact that siRNA-mediated downregulation of TRPC6 expression inhibits the proliferation of PASMCs, while single nucleotide mutations of the Trpc6 gene are associated with idiopathic pulmonary hypertension." (PMID 36935756, 2023). "A single nucleotide polymorphism in the TRPC6 gene may also cause idiopathic pulmonary hypertension." (PMID 32872338, 2020). "Moreover, several studies implicated TRPC6 in the pathogenesis of pulmonary hypertension." (PMID 28670316, 2017). "Subsequently, Pousada et al296 identified 3 more TRPC6 SNPs in the 5'-untranslated region of the TRPC6 gene that were significantly more common in a cohort of patients with idiopathic pulmonary hypertension compared with the control group." (PMID 41118703, 2025). "In the lung, studies using mouse models suggest that TRPC6 is essential for the regulation of hypoxia-mediated pulmonary vasoconstriction and pulmonary hypertension." (PMID 41118703, 2025). "Under pathological conditions such as pulmonary hypertension, changes in TRPC6 expression and function affect SOCE." (PMID 39425532, 2024). "TRPC6 has been embraced as a promising therapeutic target for a variety of diseases including gastric cancer, pulmonary hypertension, and heart disease, and a variety of new substances targeting TRPC6 are being developed." (PMID 36661921, 2023). "TRPC6 is another calcium channel expressed by SMCs, which positively controls vasoconstriction, pulmonary arterial hypertension and edema formation." (PMID 30914724, 2019). "Enhanced expression of Trpcs, including Trpc6, plays a critical role in the increase of pulmonary vascular tone in experimental model of pulmonary hypertension induced by chronic hypoxia exposure." (PMID 28085954, 2017). "TRPC3 and TRPC6 are upregulated in idiopathic pulmonary hypertension and an siRNA-induced decrease of TRPC6 expression decreases proliferation of cultured pulmonary artery VSMC isolated from patients with pulmonary hypertension." (PMID 27037223, 2016). "Additionally, sildenafil and sodium tanshinone IIA sulfonate suppresses TRPC1 and TRPC6 expressions in the treatment of experimental pulmonary hypertension." (PMID 34174803, 2021).
renal fibrosis (18 papers, 2019 to 2025). A final common manifestation of a wide variety of chronic kidney diseases characterized by glomerulosclerosis and tubulointerstitial fibrosis. "TRPC6 knockout has been shown to reduce glomerular manifestations of disease in several of these models and reduces renal fibrosis caused by urinary tract obstruction." (PMID 36421724, 2022). "In our previous study using Trpc6–/– mice, we found that TRPC6 deficiency ameliorated renal fibrosis and immune cellular infiltration in the UUO model." (PMID 35743312, 2022). "Mutations and over-activation in TRPC6 channel activity play an important role in podocyte damage in DN, However its role in renal fibrosis and the interaction with the Wnt signaling pathway in renal fibrosis still need further study." (PMID 34483931, 2021). "Interestingly, in a murine model of kidney injury (unilateral ureteral obstruction (UUO)), Trpc6−/− deficiency and pharmacological blockade with BI-749327 ameliorated renal fibrosis in C57BL/6J mice." (PMID 35743312, 2022). "The data also indicates that inhibition of TRPC6 channels triggers a Prnp transcription factor regulatory network, which contributes to the alleviation of renal fibrosis." (PMID 40525246, 2025). "Inhibition of TRPC6 channels triggers a Prnp transcription factor regulatory network, which contributes to the alleviation of renal fibrosis." (PMID 40525246, 2025). "Transient receptor potential canonical 6 (TRPC6) channel inhibition mitigates tubular injury and renal fibrosis in murine models of unilateral ureteral obstruction (UUO) and 2‐month chronic post–ischemia‐reperfusion injury (2m post‐I/R)." (PMID 40525246, 2025). "The non-immunological role of TRPC6 in the pathogenesis of UUO has been shown previously as the inhibition of TRPC6 in interstitial fibroblasts using BTP2 decreased renal fibrosis." (PMID 38003608, 2023). "Recent research has indicated that TRPC6 mediates renal fibrosis and that TRPC6 knockout ameliorates kidney fibrosis." (PMID 34937917, 2022). "The inhibition of the transient receptor potential cation channel subfamily C member 6 (TRPC6) has been found to ameliorate renal outcomes in the unilateral ureteral obstruction (UUO) of accelerated renal fibrosis." (PMID 35743312, 2022). "Taken together, these data suggest that renal fibrosis and inflammatory reactions are ameliorated in response to in vivo TRPC6 inhibition by SH045." (PMID 35743312, 2022). "In our previous study, we have shown that TRPC6 contributes to renal fibrosis and immune cell infiltration in a murine UUO model using Trpc6−/− mice." (PMID 35194063, 2022). "The potential role of TRPC3 and TRPC6 in renal fibrosis has been studied in an animal model of UUO induction, and both of them are upregulated in the obstructed kidney." (PMID 36277193, 2022). "Recent evidence strongly suggests that TRPC6 also contributes to renal fibrosis and immune cell infiltration in the unilateral ureteral obstruction mouse model of progressive renal interstitial fibrosis." (PMID 35194063, 2022). "A more robust protective effect of TRPC6 knockout than that observed here was reported in a quite distinct model of renal fibrosis that was examined in mice." (PMID 33918778, 2021). "Klotho as a regulator of calcium homeostasis inhibits transient receptor potential channel 6 (TRPC6)-mediated Ca2+ influx in cultured mouse podocytes and ameliorates albuminuria and renal fibrosis 41,42." (PMID 33162804, 2020). "Considered together, these data demonstrate that HKC protection against renal fibrosis is through TRPC6 dependent pathway." (PMID 32719603, 2020). "We further demonstrate that HKC protection of renal fibrosis is dependent on TRPC6 pathway, possibly through direct inhibition of TRPC6 channel activity and indirect suppression of TRPC6 expression." (PMID 32719603, 2020).
renal fibrosis (continued). "In addition, Huangkui capsule, an herbal adjuvant therapy propagated for chronic kidney disease (CKD), reduced the influx of macrophages into the kidneys and consequently reduced the progression of renal fibrosis via the inhibition of TRPC6." (PMID 38003608, 2023). "Further studies of the TRPC6 modulation of renal fibrosis using single-cell RNA sequencing could help to better understand the exact mechanism(s) of action in the different cell types." (PMID 35743312, 2022). "TRPC6 knockout has also been examined in the albumin overload (AO) model of renal fibrosis in rats." (PMID 36421724, 2022). "In addition, a structurally distinct TRPC6 inhibitor known as SH045 reduces renal fibrosis in an obesity model of metabolic syndrome." (PMID 36421724, 2022). "Overall, the understanding of TRPC3 and TRPC6 in renal fibrosis pathogenesis has expanded in recent years and may facilitate the development of emerging therapeutic strategies." (PMID 36277193, 2022). "In the present study, we hypothesized that the novel selective TRPC6 inhibitor SH045 (larixyl N-methylcarbamate) ameliorates UUO-accelerated renal fibrosis in a New Zealand obese (NZO) mouse model, which is a polygenic model of metabolic syndrome." (PMID 35743312, 2022). "Recent studies have shown that TRPC6 is a pivotal player in the progression of renal fibrosis." (PMID 32719603, 2020). "Similarly, the degree of HKC (1.5 g/kg/day) suppressed renal fibrosis in WT UUO mice is comparable to that observed in TRPC6 KO mice after UUO." (PMID 32719603, 2020). "An interesting finding is that HKC protection against renal fibrosis is through TRPC6 channels." (PMID 32719603, 2020). "Interestingly, our results show that SH045 inhibits the overexpression of these chemokines and the infiltration of numerous immune cells, suggesting that TRPC6 inhibition may antagonize renal fibrosis by affecting inflammatory processes." (PMID 35743312, 2022). "Studies have demonstrated that TRPC6 and NFAT form a mutual positive feedback loop that aggravates the renal fibrosis." (PMID 36277193, 2022). "Research has demonstrated that TRPC6 and NFAT form mutually positive feedback loop that exacerbates the renal fibrosis." (PMID 32719603, 2020). "TRPC3 is highly homologous to TRPC6 and TRPC3 KO mouse also displayed attenuated renal fibrosis in a UUO mouse model." (PMID 32719603, 2020). "Research has proposed that TRPC6 and NFAT form mutually positive feedback loop that exacerbates the renal fibrosis." (PMID 32719603, 2020). "HKC significantly suppressed UUO-induced expressions of TRPC6, CnA, and NFAT suggesting that HKC protection against renal fibrosis is likely through TRPC6/CnA/NFAT signaling pathway." (PMID 32719603, 2020). "However, whether the direct inhibition of TRPC6 is exclusively responsible for HKC protection against renal fibrosis is arguable since flavonoids, the main active compounds in HKC, have been reported to modulate inflammation, a critical factor driving renal fibrosis." (PMID 32719603, 2020). "TRPC6 is considered to be another key TRPC channel subtype in the progression of renal fibrosis." (PMID 36277193, 2022). "It has been reported that TRPC6 channels regulate CXC chemokine receptor 2 (CXCR2)-related chemotaxis by mediating Ca2+ influx, promoting renal tubular cell senescence and renal fibrosis by inducing mitochondrial dysfunction." (PMID 36277193, 2022). "TRPC6 is a Ca2+ permeable, non-selective cation channels that have been shown to be involved in renal fibrosis." (PMID 32719603, 2020). "Pharmacological blockade of TRPC6 ortholog, TRPC3, inhibits fibroblast proliferation and myofibroblast differentiation and genetic ablation of TRPC3 attenuates UUO-induced renal fibrosis in mice." (PMID 32719603, 2020). "Therefore, it is likely that direct suppression of TRPC6 activity contributes to HKC inhibited TRPC6/CnA/NFAT expression, which is responsible for TGF-β signaling critical for the progression of renal fibrosis." (PMID 32719603, 2020).
renal fibrosis (continued). "To date, no study uncovered the role of TRPC6 on the EMT in renal fibrosis." (PMID 33520986, 2020). "Lastly, both TRPC3 and TRPC6 mRNA were potently upregulated in interstitial fibroblasts of obstructed kidneys, but combined TRPC3 and TRPC6 knockout in UUO provided no additional protection from renal fibrosis compared to TRPC6 knockout mice." (PMID 31877991, 2019).
Hypertension (17 papers, 2008 to 2025). The presence of chronic increased pressure in the systemic arterial system. "In the current study, rs1938859 in the transient receptor potential channel C6 (TRPC6) gene was also associated with hypertension." (PMID 35448080, 2022). "Polymorphisms in the upstream region of the TRPC6 gene could also result in new-onset hypertension through the RAS." (PMID 35448080, 2022). "Autoregulatory impairment was most pronounced in hypertensive IGF-1 deficient mice, who also failed to exhibit the protective increase in myogenic tone and protective increases in TRPC6 channel expression that accompany hypertension in control mice." (PMID 36755922, 2023). "After opioid-induced podocyte injury, the existing podocytes sustained additional injury as a consequence of overexpression of TRPC6 channels in hypertension, which forms a vicious circle." (PMID 33046522, 2020). "Studies have shown that TRPC6 channel is expressed in microglia and involved in microglial activation and neuroinflammatory response in different diseases including hypertension, epilepsy, Alzheimer's disease, infectious diseases and neuropathic pain." (PMID 33604333, 2020). "The overexpression of TRPC6 channels during the development of hypertension provided an additional source for Ca2+ entry and triggered an excessive Ca2+ influx through the κ-OR/TRPC6 pathway in the case of opioid treatment." (PMID 33046522, 2020). "In conclusion, the present work represents the first evidence of the role of κ-OR/TRPC6 signaling in the control of calcium handling in podocytes and reveals the mechanism by which opioids exacerbate kidney damage in hypertension." (PMID 33046522, 2020). "The studies conducted on these channels indicated that TRPM4, TRPC1, TRPC3, and TRPC6 channels play an important role in the creation and progression of hypertrophy and hypertension." (PMID 32641948, 2019). "In vivo, the upregulation of TRPC6 was much more clearly demonstrated in cardiovascular pathologies such as hypertension, hypertrophy and increased endothelial permeability." (PMID 18452628, 2008). "We conclude that the pharmacological inhibition of TRPC6 might be a promising antifibrotic therapeutic method to treat progressive tubulo-interstitial fibrosis in hypertension and metabolic syndrome." (PMID 35743312, 2022). "Indeed, compensatory increases in TRPC3 can lead to an increase in contractility of vascular smooth muscle and hypertension in TRPC6 knockout mice, although the extent to which this occurs depends on genetic background." (PMID 36421724, 2022). "However, independent studies demonstrated that TRPC6 was upregulated under hypertension, using for example deoxycorticosterone acetate-salt hypertensive rats model or the Milan hypertensive strain (MHS)." (PMID 32854408, 2020). "Here, we show, for the first time that stimulation of G protein–coupled κ-ORs in rats and human kidney tissue leads to a transient elevation in podocyte [Ca2+]i via κ-OR/TRPC6 signaling pathway, which is activated during hypertension, and aggravates podocyte and renal damage." (PMID 33046522, 2020). "However, it is unknown whether TRPC6 inhibition is effective for inhibiting progressive tubulo-interstitial fibrosis in hypertension and metabolic syndrome." (PMID 35743312, 2022). "Notably, the TRPC6 KO mice presented with hypertension and increased receptor-operated contractility due to upregulated expression of constitutively active TRPC3-type channels in the TRPC6 KO mouse vasculature." (PMID 32872338, 2020). "Functional maladaptation of aged cerebral arteries to hypertension is partly due to the dysregulation of the transient receptor potential canonical channel 6 (TRPC6), which is a non-selective cation channel from the transient receptor potential (TRP) ion channel superfamily." (PMID 36755922, 2023).